ATOX1 (antioxidant 1 copper chaperone)
Description:
Binds and deliver cytosolic copper to the copper ATPase proteins. May be important in cellular antioxidant defense.
Synonyms: HAH1; ATX1
Tractability: Small molecule: a structure with a bound ligand is known. Antibody: the Human Protein Atlas places it where antibodies can reach. PROTAC: ubiquitination databases record sites on it; its protein half-life has been measured.
Gene: Protein-coding gene on chromosome 5 (151,738,084 to 151,772,532, reverse strand). Ensembl gene ENSG00000177556.
Subcellular location (Human Protein Atlas): Nucleoplasm; Plasma membrane
Pathways (Reactome):
Cellular responses to stimuli: Detoxification of Reactive Oxygen Species
Immune System: Ion influx/efflux at host-pathogen interface
Gene Ontology:
Molecular function: copper chaperone activity; copper ion binding; copper-dependent protein binding; cuprous ion binding; protein binding; DNA-binding transcription activator activity, RNA polymerase II-specific; metallochaperone activity; ATPase binding; metal ion binding
Biological process: regulation of removal of superoxide radicals; copper ion transport; intracellular copper ion homeostasis; response to oxidative stress; copper ion export; negative regulation of apoptotic process; positive regulation of transcription by RNA polymerase II
Cellular component: cytosol; nucleus
Genetic constraint (gnomAD): Loss-of-function variants: 4 observed, 6.66 expected, observed/expected ratio (o/e) 0.6, 90% interval 0.29 to 1.36. That is too few expected variants to judge how well the gene tolerates losing a copy. Missense variants: 68 observed, 83.09 expected, observed/expected ratio (o/e) 0.82, 90% interval 0.67 to 1. Synonymous variants: 25 observed, 29.45 expected, observed/expected ratio (o/e) 0.85, 90% interval 0.62 to 1.19.
Homologues: Orthologues: chimpanzee ATOX1 (97% identical), macaque ATOX1 (93% identical), rat Atox1 (87% identical), mouse Atox1 (85% identical), dog ATOX1 (81% identical), guinea pig ATOX1 (76% identical), rabbit ATOX1 (76% identical).
Diseases named in the same sentence as ATOX1 in open-access papers:
ATOX1 is named in the same sentence as 60 diseases in open-access papers, as found by Europe PMC text mining. Sharing a sentence is not in itself a finding about the gene and the disease. The quoted sentences say what the papers report.
breast carcinoma (27 papers, 2010 to 2025). "We therefore studied the association of ATOX1 expression levels with clinicopathological parameters and survival for 1904 breast cancer patients using the METABRIC data set." (PMID 31898157, 2020). "In conclusion, ATOX1 may be a potential predictive biomarker for TM treatment of breast cancer patients at high risk of recurrence and should be tested in a larger cohort of patients." (PMID 34944703, 2021). "Further molecular-mechanistic studies of the underlying pathways, which result in ATOX1 expression levels being correlated with breast cancer patient survival, may allow for the discovery of new cancer drug targets." (PMID 31898157, 2020). "Since most cancer-related deaths are due to metastasis, we hypothesized that ATOX1 mRNA expression may be associated with breast cancer disease progression and thus, a prognostic biomarker in breast cancer." (PMID 31898157, 2020). "Taken together, cytoplasmatic ATOX1 has the potential to be a predictive biomarker for TM treatment of breast cancer patients at high risk of recurrence, such that patients with high cytoplasmatic ATOX1 levels in the cancer tissue might benefit from TM treatment." (PMID 34944703, 2021). "As local cell movement is facilitated by the formation of actin filament-enriched extensions of the plasma membrane at the leading edge of the cell as exemplified by lamellipodia, ATOX1 accumulates at lamellipodia borders of migrating breast cancer cells." (PMID 40721800, 2025). "Accordingly, ATOX1 inhibition prevents angiogenesis and tumor growth in a xenograft mouse model of breast cancer." (PMID 40721800, 2025). "ATOX1 mediates the metastasis of breast cancer cells through coordinated copper transport along the ATP7A-LOX axis, making the levels of ATOX1 in tumor cells a potential predictive marker of metastatic potential and a biomarker for copper depletion therapy." (PMID 40341098, 2025). "Elevated ATOX1 expression has been found to be correlated with unfavorable prognosis among individuals diagnosed with early‐stage breast cancer." (PMID 39676279, 2024). "Copper and its associated proteins, including ATOX1 and CCS, play notable roles in breast cancer progression, metastasis, and poor clinical outcomes." (PMID 39867656, 2024). "Research has indicated that breast cancer cell migration is influenced by the copper chaperone ATOX1." (PMID 39036924, 2024). "The ATOX1 is observed to accumulate at the borders of lamellipodia in migrating breast cancer cells." (PMID 39676279, 2024). "Although only indirect evidence of in-cell interaction, proximity studies in breast cancer cells show Memo1 and Atox1 to be spatially close." (PMID 36067318, 2022). "To link the in vitro interaction data to cells, we used a proximity ligation assay (PLA) to test for Atox1 and Memo1 proximity in breast cancer cells." (PMID 36067318, 2022). "This correlates with the prognostic value of ATOX1 which was found to possess similar properties in the breast cancer." (PMID 36296659, 2022). "In accord, poor survival of breast cancer patients correlates with high Atox1 expression in the tumor." (PMID 36067318, 2022). "Complementary proximity ligation experiments in MDA-MB-231 breast cancer cells imply interactions of Atox1 and Memo1 in living cells." (PMID 36067318, 2022). "ATOX1 expression was evaluated in whole breast tumor tissue from breast cancer patients enrolled in the phase II clinical trial of TM using immunohistochemical staining." (PMID 34944703, 2021). "Individual cell migration is an early step in breast cancer metastasis; thus, ATOX1 silencing decreases the breast cancer cell migration velocity via coordinated copper transport in the ATP7A-LOX (proenzyme of lysyl oxidase) axis." (PMID 34504870, 2021).
breast carcinoma (continued). "Nonetheless, cell migration, allowing for metastasis, is a common process in all subtypes and we earlier found that ATOX1 plays a role in breast cancer cell migration in cell culture studies, although the underlying pathways are not yet established." (PMID 31898157, 2020). "The copper chaperone ATOX1 was recently shown to play a role in breast cancer cell migration, which is a key step in metastasis." (PMID 31898157, 2020). "Our results indicate ATOX1 expression levels as a potential prognostic biomarker for ER-positive subtypes and early stages of breast cancer." (PMID 31898157, 2020). "The nuclear localization of Atox1 was also correlated with increased migration capabilities in breast cancer cells in an ATP7A- and LOX-dependent mechanism." (PMID 33271772, 2020). "We recently showed that Atox1 facilitates breast cancer cell migration and, upon analyzing breast cancer patient tumor data, high Atox1 levels in the tumors correlated with worse prognosis of patient survival." (PMID 32506305, 2020). "Cell migration is also a key step in cancer metastasis and the human copper chaperone Atox1 was recently found to facilitate this process in breast cancer cells." (PMID 32506305, 2020). "Our analysis revealed that, with respect to ATOX1, it is upregulated in breast, colorectal, uterus and liver tumors, and the breast cancer data were confirmed by us in tissue microarray experiments." (PMID 31898157, 2020). "This demonstrates that the ATOX1 expression level correlates with patient survival only in specific molecular subtypes of breast cancer." (PMID 31898157, 2020). "Nevertheless, using a wound-healing assay, they determined that ATOX1 is required for breast cancer cell migration in vitro." (PMID 33912613, 2018). "When we turned to cell line studies, we stumbled on a putative functional role for ATOX1 in breast cancer cells." (PMID 28425924, 2017). "Using an aggressive breast cancer cell line, we made the discovery that ATOX1 accumulates at lamellipodia borders of migrating breast cancer cells and ATOX1 silencing resulted in migration defects as evidenced from reduced wound closure." (PMID 28425924, 2017). "Mapping of gene expression signatures in breast cancer cell lines has noted upregulation of ATOX1 via proteomics." (PMID 28425924, 2017). "Using immunohistochemistry, we investigated ATOX1 in 67 breast cancer sections in tissue microarrays (TMAs)." (PMID 28425924, 2017). "In accord, it was shown that targeting of cysteine-containing Cu-transporting proteins (e.g., ATP7A/B, ATOX1) with ammonium tetrathiomolybdate enhanced sensitivity of breast cancer cells to cisplatin." (PMID 28425924, 2017). "Scoring of the 67 breast cancer samples revealed that the highest ATOX1 intensities were found in samples of all cancer molecular subtypes but the HER2 subtype." (PMID 28425924, 2017). "Aberrant expression of 3 novel breast cancer-associated proteins namely AK1, ATOX1 and HIST1H2BM were subsequently validated via immunoblotting of the MCF10AT model and immunohistochemistry of progressive clinical breast cancer lesions." (PMID 20543960, 2010). "It would be interesting to conduct further studies on ATOX1 that should provide new insights into the role and mechanism of ATOX1 in breast cancer biology." (PMID 20543960, 2010). "ATOX1 is overexpressed in breast cancer, colon cancer, lung cancer, melanoma, and multiple myeloma." (PMID 40721800, 2025). "The expression of the copper chaperone ATOX1 is significantly upregulated in breast cancer cells." (PMID 39676279, 2024). "In addition, the ATOX1-ATP7A-LOX axis is necessary for breast cancer cell migration, and high levels of ATOX1 often indicate poor patient survival." (PMID 37767404, 2023). "Analysis of transcription profiling of 1904 breast cancer patients on METABRIC data set suggests that overexpression of Atox1 may serve as a marker for breast cancer prognosis but only in the hormone receptor-positive tumors." (PMID 36296659, 2022).
breast carcinoma (continued). "In addition, we recently reported that ATOX1 stimulates directional breast cancer cell migration, a key step in metastasis, and that high tumor expression of ATOX1 significantly correlates with poor survival of breast cancer patients." (PMID 34944703, 2021). "In breast cancer cells, ATOX1 supports the metastatic process." (PMID 34988012, 2021). "Among the copper-binding proteins, ATOX1 displays a high concentration in breast cancer cells." (PMID 34988012, 2021). "As 90% of all cancer-related deaths are due to metastasis, this finding suggests that ATOX1 may play a crucial role in processes facilitating breast cancer metastasis like cancer cell migration." (PMID 31898157, 2020). "Moreover, when imaging cells, we found ATOX1 to be localized at lamellipodia edges of aggressive breast cancer cells." (PMID 31898157, 2020). "This suggests that ATOX1 may participate in breast cancer-related processes leading to patient deaths." (PMID 31898157, 2020). "To assess the putative role of ATOX1 as a prognostic biomarker in breast cancer patients, we here investigated the correlation between ATOX1 mRNA expression levels and patient survival using the Molecular Taxonomy of Breast Cancer International Consortium (METABRIC) breast cancer database." (PMID 31898157, 2020). "Next, we investigated ATOX1 expression vs. survival outcome at different stages of breast cancer." (PMID 31898157, 2020). "Moreover, it has been shown that Atox1 has a role in the migration of cancer cells in breast cancer." (PMID 33271772, 2020). "Taken together, our data indicate that the ATOX1 expression level can be used as a biomarker in early stages of breast cancer, whereby high ATOX1 levels correlate with worse survival prognosis in Luminal A, Luminal B and Normal-like (and Claudin low when considering OS data) tumors." (PMID 31898157, 2020). "Thus, the ATOX1 expression level appears to be a determinant of survival only at early stages of breast cancer." (PMID 31898157, 2020). "Atox1 may be a potential prognostic biomarker for estrogen-receptor (ER)-positive and early stages of breast cancers because increased expression levels of Atox1 correlated with poor survival for stages 1 and 2 breast cancers." (PMID 33271772, 2020). "In addition, we found Atox1 to localize to membrane protrusions in migrating breast cancer cells, further supporting a role for Atox1 in cell migration." (PMID 32506305, 2020). "Evaluation of the different PAM50 molecular subtypes using the METABRIC breast cancer data set shows significant correlations between high ATOX1 expression and decreased DSS for Luminal A, Luminal B and Normal-like breast tumors, but not for Claudin low, Basal-like and HER2-enriched tumors." (PMID 31898157, 2020). "ATOX1, AK1 and HIST1H2BM have been validated as novel-breast cancer associated proteins." (PMID 20543960, 2010). "In support of biological relevance, we show that the cytoplasmic Cu chaperone Atox1, which delivers Cu(I) in the secretory pathway, can interact with and exchange Cu(I) with Memo1 in vitro and that the two proteins exhibit spatial proximity in breast cancer cells." (PMID 36067318, 2022). "Moreover, they demonstrated the overexpression of the ATOX1 chaperone in breast cancer." (PMID 36291728, 2022). "Thus, ATOX1 expression portends a survival disadvantage in breast cancer patients." (PMID 31898157, 2020). "Thus, ATOX1 may have an unknown role in breast cancer cell migration, that parallels the reported role for ATOX1 in endothelial cell wound healing." (PMID 28425924, 2017). "Accordingly, immunofluorescence staining revealed partial colocalization of ATOX1, ATP7A and LOXPP, c, at the lamellipodial borders of breast cancer cells." (PMID 40721800, 2025). "DC_AC50-dependent inhibition of ATOX1 and reduced GSH levels increase the vulnerability of basal-like breast cancer cells to copper imbalance and oxidative stress." (PMID 40721800, 2025).
breast carcinoma (continued). "The silencing of Atox1 expression resulted in a decrease in LOX activity and inhibited the migration of breast cancer cells, indicating that ATOX1’s role in the ATP7A–LOX signaling pathway is associated with metastasis." (PMID 38918694, 2024). "We identified 13 members of the copper transport system associated with the occurrence, progression, and mortality of breast cancer, including SLC31A1, DMT1, ATP7A, ATP7B, MTs, GSH, ATOX1, CCS, COX17, SCO1, SCO2, and COX11." (PMID 39676279, 2024). "For example, the increased expression of ATOX1 and MADCAM1 in MDA-MB-231 breast cancer cells corresponded with their promoter hypomethylation in canine DCIS and invasive cancer samples." (PMID 32051475, 2020). "Nevertheless, both genes follow cancer-specific patterns of amplification, with Atox1 and CCS being amplified at a maximal level in kidney renal-cell carcinoma (KIRC) (23.1%) and breast cancer (BRCA) (18.1%) diseases, respectively." (PMID 31575544, 2019). "In addition to the regulation of cyclin D1 levels, the contribution of ATOX1 to cell cycle progression can include its direct interaction with subunits of the anaphase-promoting complex (APC), as demonstrated in HEK293T and breast cancer cells." (PMID 40721800, 2025). "ATOX1 regulates intracellular copper transport to key proteins such as ATP7A, ATP7B, and SOD1, while also promoting inflammatory neovascularization, wound healing, and the migration of breast cancer cells." (PMID 39867656, 2024). "Antioxidant 1 copper chaperone (ATOX1) could promote copper transport via ATP7A-LOX signaling, leading to metastasis of breast cancer cells." (PMID 37380924, 2023). "Another important finding is that elevated ATOX1 expression selectively correlates with poor survival for breast cancer stages 1 and 2, but not for stage 3." (PMID 31898157, 2020). "From extensive literature search, AK1, ATOX1 and HIST1H2BM were among the few whose aberrant expressions have not been previously associated with breast cancer development." (PMID 20543960, 2010). "Similarly, breast cancer is characterized by the overexpression of CTR1, ATP7B, ATOX1, and COX17." (PMID 41516324, 2025). "We found a strong correlation between high ATOX1 mRNA levels and reduced DSS for Normal-like (median DSS of 161 months for low ATOX1 vs. 64 months for high ATOX1, p = 0.005), Luminal A (171 vs. 91 months, p = 0.002) and Luminal B (158 vs. 67 months, p = 0.001) breast cancer subtypes." (PMID 31898157, 2020). "With respect to molecular mechanistic studies of Cu proteins’ roles in breast cancer, there is such information reported for ten proteins and below we discuss findings for selected proteins of the ten (MEMO1, SPARC, LOX, and some LOX-like proteins), followed by a separate section about ATOX1." (PMID 28425924, 2017). "We found that high ATOX1 levels in the tumor cell cytoplasm, but not ATOX1 in the nucleus, correlated with a trend towards better EFS when considering all breast cancer subtypes (i.e., Luminal, HER2 and TNBC)." (PMID 34944703, 2021). "We found that breast cancer patients at stage III of disease with high cytoplasmatic ATOX1 levels in their primary tumor have a 65% higher EFS chance after copper depletion treatment with TM (median EFS is 40.4 months for low ATOX1 patients, while not yet reached for high ATOX1 patients)." (PMID 34944703, 2021).